HPGD (15-hydroxyprostaglandin dehydrogenase)
Diseases named in the same sentence as HPGD in open-access papers (continued):
Sharing a sentence is not in itself a finding about the gene and the disease.
autosomal recessive inherited disease (1 paper, 2018). "PHO is an autosomal recessive inherited disease that is classified into two subtypes based on its causal gene, one being the HPGD gene and the other the SLCO2A1 gene." (PMID 29313109, 2018).
HPGD also shares sentences with these, for which no sentence is quoted: sarcopenia (5 papers); adenoma (4); lung adenocarcinoma (4); inflammatory bowel disease (3); anaphylaxis (2); Autosomal recessive pachydermoperiostosis (2); depression (2); Insulin resistance (2); non-small cell lung carcinoma (2); rheumatoid arthritis (2); Stroke (2); tendinopathy (2); abdominal aortic aneurysm (1); acute myeloid leukemia (1); Alzheimer disease (1); aplastic anemia (1); Arthritis (1); autosomal recessive primary hypertrophic osteoarthropathy 1 (1); breast lobular cancer (1); breast medullary cancer (1); cardiovascular disease (1); cerebral infarction (1); chorioamnionitis (1); chronic gastritis (1); colon (1); colon adenocarcinoma (1); colon adenoma (1); colorectal adenocarcinoma (1); congenital heart disease (1); Ellis-van Creveld syndrome (1).
A further 42 diseases each share a sentence with HPGD in 1 paper.